COMP (cartilage oligomeric matrix protein)
Diseases named in the same sentence as COMP in open-access papers (continued):
Sharing a sentence is not in itself a finding about the gene and the disease.
atherosclerosis (15 papers, 2015 to 2025). A disease characterized by the build-up of fatty material and calcium deposition in the arterial wall resulting in partial or complete occlusion of the arterial lumen. "COMP deficiency leads to accelerated atherosclerosis, plaque calcification, and post injury restenosis." (PMID 33889574, 2021). "The degradation of COMP has been associated with atherosclerosis progression in patients with symptomatic carotid stenosis by measuring circulating levels of COMP and its fragments." (PMID 33889574, 2021). "COMP−/− mice are more susceptible to post-injury restenosis, atherosclerosis, vascular calcification and thrombosis formation." (PMID 29867124, 2018). "Vascular smooth muscle cells are sensitive to shear forces which regulate COMP expression in vascular tissues in atherosclerosis and in carotid stenosis." (PMID 41009743, 2025). "The ADAMTS7 rs3825807 G allele has been noted to affect ADAMTS7 maturation, while COMP cleavage and VSMC migration has been linked with subclinical atherosclerosis." (PMID 31460868, 2019). "We recently also demonstrated that COMP negatively regulates atherosclerosis and lesional calcification formation via direct interaction with integrin β322." (PMID 29867124, 2018). "Previous studies demonstrated that ADAMTS-7 facilitates vascular muscle cell migration and intimal thickening after vascular injury and plays an important role in atherosclerosis and restenosis by degrading COMP." (PMID 25885961, 2015). "Notably, treatment with a COMP-derived peptidomimetic (CCPep24) that mimics COMP’s interaction with integrin α5 reduced endothelial activation and atherogenesis in vivo, indicating the protective role of COMP in EC inflammation and atherosclerosis." (PMID 41300494, 2025). "Animal studies have shown that bone marrow transplantation of ApoE−/−COMP−/− mice to ApoE−/− mice increases the formation of atherosclerotic plaques, suggesting that bone marrow-derived COMP may play a crucial role in preventing atherosclerosis." (PMID 36012514, 2022). "It has been suggested that enhanced sCOMP levels result from the proteolytic activity of ADAMTS-7 (a disintegrin and metalloproteinase with thrombospondin motifs-7), which promotes the degradation of COMP in blood vessels and thus mediates vascular calcification and atherosclerosis." (PMID 31963737, 2020). "Therefore, it is tempting to speculate a possible association of arterial COMP expression with TGF-β-dependent signaling in EC inflammation responsible for EndMT, atherosclerosis, and vascular calcification." (PMID 41300494, 2025). "Moreover, COMP or COMP-derived peptidomimetics (CCPep24) can protect endothelial cells from flow-induced inflammatory responses by blocking aberrant integrin α5 activation, thus inhibiting atherosclerosis pathogenesis." (PMID 36012514, 2022). "Genes such as COMP (cartilage oligomeric matrix protein), CHI3L1, PLA2G2A, P2RY12, CR1, HPSE (heparanase), PTX3 and SERPINE1 were related to atherosclerosis." (PMID 34218797, 2021). "The rs3825807 G/G genotype in the ADAMTS7 locus, has been linked with reduced prevalence and severity of atherosclerosis, yet does not appear to reduce the expression of ADAMTS7 but its maturation and activity, resulting in reduced COMP cleavage and attenuated VSMC migration." (PMID 31460868, 2019).
liver fibrosis (15 papers, 2017 to 2025). "Recently, pathogenesis of various fibrotic diseases, such as liver fibrosis and renal fibrosis, has been linked to COMP deposition." (PMID 37082197, 2023). "Serum COMP has been demonstrated to be a sensitive non-invasive diagnostic biomarker for liver fibrosis." (PMID 36012514, 2022). "Our findings have been supported by a previous clinical study revealing a positive association between serum COMP concentrations and stage of liver fibrosis in HCV-infected patients." (PMID 34404836, 2021). "Notably, we also found that elevated circulating COMP levels were independently associated with degree of liver fibrosis in BA patients." (PMID 34404836, 2021). "Indeed, circulating COMP levels were found to be independently associated with degree of liver fibrosis in the patients." (PMID 34404836, 2021). "Although an involvement of COMP in pathogenesis of liver fibrosis has been clarified, whether its protein levels in the systemic and local environments were associated with severity of liver fibrosis in post-operative BA patients remains to be determined." (PMID 34404836, 2021). "In biliary atresia, a devastating pediatric liver disease, cartilage oligomeric matrix protein (COMP) was identified as a progressive marker of liver fibrosis." (PMID 40625923, 2025). "COMP promotes the progression of hepatic fibrosis via CD36/MEK/ERK signaling to facilitate collagen-I deposition in hepatic stellate cells." (PMID 36012514, 2022). "Liver fibrosis is associated with major alterations in both quantity and composition of ECM, and COMP directly indicates ECM turnover in the liver." (PMID 35845304, 2022). "Raised circulating COMP levels were found to be independently correlated with degree of liver fibrosis." (PMID 34404836, 2021). "Taken together, circulating COMP appears to have potential as a non-invasive biomarker for BA progression—particularly hepatic fibrosis." (PMID 34404836, 2021). "When severity of liver fibrosis was considered, circulating COMP levels were significantly elevated in BA patients with fibrosis, compared with the patients without fibrosis and healthy controls (P = 0.03, P < 0.001, respectively)." (PMID 34404836, 2021). "Elevations in serum levels of COMP have recently been shown to correlate with the presence and the degree of hepatic fibrosis by liver elastography (r = 0.71, p<0.001)." (PMID 28114331, 2017). "Studies have shown that COMP expression is increased in liver fibrosis, and also cardiac fibrosis." (PMID 39388499, 2024). "This circumstance may help us explain why increased COMP protein levels were found to be related to degree of liver fibrosis in BA patients." (PMID 34404836, 2021). "In addition to this, it has been shown that circulating COMP levels were positively correlated with degree of liver fibrosis in patients with chronic hepatitis C virus (HCV) infection." (PMID 34404836, 2021). "As currently available data are derived from in-depth analyses of these relationships, future validation with prospective studies is needed to confirm the potential of circulating COMP as a biomarker for progression of liver fibrosis in post-operative BA patients." (PMID 34404836, 2021). "However, the molecular mechanisms underpinning COMP relevance to liver fibrosis in BA patients remain to be elucidated further." (PMID 34404836, 2021). "Accordingly, the purpose of this study was to measure circulating CLU levels in post-operative BA patients compared to age-matched healthy controls and to determine the possible application of circulating COMP as a non-invasive marker of liver fibrosis in those patients." (PMID 34404836, 2021). "Concordantly, COMP was suggested to foster skin, lung and liver fibrosis." (PMID 33047019, 2020). "A recent report indicated that COMP could promote the process of liver fibrosis through MEK/ERK signaling pathway." (PMID 30231922, 2018).
liver fibrosis (continued). "The association between COMP expression and presence of liver metastases may be perhaps related to the fact that COMP participates in the pathogenesis of other liver related diseases, such as liver fibrosis and can serve as biomarker of liver fibrosis in patients with chronic viral hepatitis." (PMID 31737569, 2019). "Moreover, COMP enhances the synthesis of type 1 collagen in hepatic stellate cells (HSCs) via CD36 receptor-mediated activation of MEK1/2-pERK1/2 signaling to regulate liver fibrosis." (PMID 30999932, 2019). "An emerging body of evidence has also demonstrated that hepatic stellate cell (HSC)-secreted TSP-5, which is also known as cartilage oligomeric matrix protein (COMP), stimulates CD36-mediated Akt/Erk signaling to promote liver fibrosis." (PMID 33407730, 2021). "From this, in the present study, we investigated whether a component of ECM namely COMP, which has been demonstrated to be significantly increased in the circulation of BA patients, especially those with fibrosis, may have a potential as a non-invasive biomarker of liver fibrosis." (PMID 34404836, 2021). "Given the prior literatures about liver fibrosis suggesting that COMP induced fibrillary collagen-I deposition via CD36 receptor, we wonder if CD36 was related with COMP in HCC." (PMID 30231922, 2018). "Correspondingly, circulating COMP levels remained significantly increased in BA patients without liver fibrosis, as compared to healthy controls (P < 0.001)." (PMID 34404836, 2021). "Previous researchers have demonstrated that COMP plays a key role in modulating liver fibrosis through activating MEK1/2 –pERK1/2 signaling and enhancing the synthesis of type 1 collagen in hepatic stellate cells (HSCs), and HSCs-derived COMP facilitates invasion and metastasis of HCC." (PMID 30999932, 2019). "Given that a key event participating in liver fibrogenesis is accumulation of extracellular matrix (ECM) components, cartilage oligomeric matrix protein (COMP), a non-collagenous extracellular matrix protein, is gaining increasing interest as a possible mediator for liver fibrosis." (PMID 34404836, 2021).
joint disease (13 papers, 2010 to 2026). "Supported by recent literature on the roles of MMPs, ADAMTS‐5, and COMP in joint disease, the model offers a valuable platform for future studies on OA mechanisms and therapeutic screening." (PMID 41272411, 2026). "Before the start of TNFαI therapy, serum levels of COMP significantly correlated with the patients’ ages (p < 0.05) and their 28-joint disease activity score values based on their erythrocyte sedimentation rates (DAS28-ESR; p < 0.05)." (PMID 37629227, 2023). "The relationship of serum cartilage oligomeric matrix protein (COMP) with arthropathy was evaluated in five studies with different results." (PMID 33023246, 2020). "Increase in synovial fluid and serum COMP level is used as a bio-marker for cartilage turnover in human joint diseases." (PMID 22906101, 2012). "Serum COMP level is indeed elevated in OA patients, and could serve as a prognostic biomarker for the early diagnosis of this joint disease." (PMID 34680093, 2021). "However it is notable that CILP2, like other high-scoring plasma protein markers such as COMP, TNXB, THBS4, SPP1, COL2A1 to name a few, are associated with connective tissue development (cartilage matrix synthesis in the case of CILP2) and bone and joint disorders." (PMID 22558154, 2012). "In conclusion, the present study showed that serum concentrations of a unique COMP neo‐epitope in horses represent a potential biomarker for acute joint disease that is not affected by age, short‐term training or circadian rhythms during rest." (PMID 30739342, 2019). "COMP has shown promising effects as a prognosticator of rapid joint destruction in humans with levels in both serum and SF being increased in patients with OA when compared to those without joint disease." (PMID 30208927, 2018).
colorectal cancer (12 papers, 2016 to 2025). A primary or metastatic malignant neoplasm that affects the colon or rectum. "This function of COMP may also increase the risk of colorectal cancer metastasis." (PMID 32754278, 2020). "Thus, inhibiting COMP is a promising target for cancer treatments, particularly as COMP has been found to be highly expressed in and causes increased incidence of metastasis and proliferation of multiple cancer types including, breast, prostate, and colorectal cancers." (PMID 40141111, 2025). "Mechanistically, COMP interacts with the actin-binding protein Transgelin to regulate cytoskeletal remodeling and enhance the malignant progression of colorectal cancer." (PMID 36012514, 2022). "Western blot analysis of COMP and TGF-β1 protein expression levels suggested that TGF-β1, as well as COMP, were upregulated in colorectal cancer cell lines compared with the normal colonic cell line (NCM-460)." (PMID 36551305, 2022). "COMP knockdown prevents the metastasis and invasion of colorectal cancer, while COMP overexpression enhances epithelial-mesenchymal transition (EMT)." (PMID 36012514, 2022). "A previous pan-cancer single cell analysis of ovarian, lung, and colorectal cancer, showed that COMP, COL10A1, COL11A1, and MMP1 all have higher expression in CAFs26." (PMID 34732773, 2021). "COMP expression in colorectal cancer tissues was significantly higher than that in normal tissues (p < 0.05)." (PMID 32754278, 2020). "In-depth disclosure of the molecular mechanism that affects the expression of COMP protein in colorectal cancer tissues can provide a theoretical basis for understanding the occurrence and development of colorectal cancer." (PMID 32754278, 2020). "A biological laboratory study of Chrysin was conducted in vivo and in vitro to further study the inhibitory effect of Chrysin on colorectal cancer through the COMP/TAGLN complex." (PMID 32754278, 2020). "COMP was highly expressed in the colorectal cancer tissues, as observed through weighted gene co-expression network analysis (WGCNA) and Venn analysis." (PMID 32754278, 2020). "COMP knockdown can inhibit colorectal cancer metastasis and invasion, whereas COMP overexpression promotes EMT in colorectal cancer." (PMID 32754278, 2020). "Western blot (WB) results further confirmed that the expression levels of epithelial markers (E-cadherin and occludin) were upregulated after the knockdown of COMP by colorectal cancer cells." (PMID 32754278, 2020). "The effect of COMP in the EMT of colorectal cancer cells based on the biological function analysis of COMP was studied to understand the biological significance of COMP." (PMID 32754278, 2020). "Chrysin inhibited the EMT in colorectal cancer, and this mechanism was achieved by targeting the COMP/TAGLN complex." (PMID 32754278, 2020). "COMP is highly expressed in highly malignant colorectal cancer and positively correlated with TAGLN expression." (PMID 32754278, 2020). "Patients with colorectal cancer with high COMP expression also had higher metastasis and clinical staging than those with low COMP expression." (PMID 32754278, 2020). "Scanning electron microscopy (SEM) results showed that COMP knockdown promoted epithelial changes in colorectal cancer cells, whereas COMP overexpression promoted mesenchymal phenotypic changes in colorectal cancer cells." (PMID 32754278, 2020). "Chrysin therapy and/or combined COMP knockdown were applied to the xenograft tumor models to verify the inhibitory effect of Chrysin on colorectal cancer in vivo." (PMID 32754278, 2020). "The hypergeometric distribution analysis showed that THBS2 have a higher correlation with colorectal cancer when compared with COMP (p = 0.0029)." (PMID 27632935, 2016). "Indeed, one study reported that COMP promotes the induction of epithelial-mesenchymal transition in colorectal cancer." (PMID 38563861, 2024). "COMP is also substantially expressed in highly malignant colorectal cancer." (PMID 36012514, 2022).
colorectal cancer (continued). "COMP promotes metastasis and invasion of colorectal cancer by activating the EMT pathway." (PMID 34503278, 2021). "Finally, the combination of COMP and Chrysin and the inhibitory effect of Chrysin on colorectal cancer were demonstrated through in vivo and in vitro experiments." (PMID 32754278, 2020). "Knockdown of COMP inhibited liver metastasis in colorectal cancer." (PMID 32754278, 2020). "This study found that COMP was involved in the malignant progression of colorectal cancer, and its mechanism may be related to the expression of apoptosis inhibitors induced by COMP and the inhibition of apoptosis in colorectal cancer cells." (PMID 32754278, 2020). "As a universality gene in tumor and normal tissue, COMP might not be considered as a biomarker associated with colorectal cancer." (PMID 27632935, 2016). "Furthermore, COMP expression was positively correlated with 23 different types of collagens when their co-expression was investigated with the cBioPortal analyzing RNA expression data from the TCGA project stratified for colorectal cancer patients (TCGA, Firehose Legacy)." (PMID 37207219, 2023). "Chrysin can directly act on the COMP/TAGLN interaction interface and inhibit mesenchymal transformation, thereby hindering the malignant progression of colorectal cancer." (PMID 32754278, 2020). "The role of COMP and TAGLN in colorectal cancer was fully described by combining bioinformatics analysis and functional and mechanistic studies." (PMID 32754278, 2020). "The correlation analysis between the expression level of COMP and cell function showed that the expression of COMP was positively correlated with EMT, angiogenesis, metastasis, and invasion of colorectal cancer cells." (PMID 32754278, 2020). "COMP and TAGLN showed significant co-localization at the colorectal cancer tissue levels ((Pearson's correlation = 0.9711)." (PMID 32754278, 2020). "Therefore, COMP/TAGLN may be a potential target for colorectal cancer therapy." (PMID 32754278, 2020). "The correlation between the expression of COMP and TAGLN was analyzed by using the sequencing data from patients with colorectal cancer in The Cancer Genome Atlas (TCGA) database." (PMID 32754278, 2020). "For instance, DNAH5 (dynein axonemal heavy chain 5) has an important role in the development of colorectal cancer, whereas COMP (cartilage oligomeric matrix protein) has been recently reported as a novel biomarker contributing to the severity of BC." (PMID 28981577, 2019). "We recently reported that high levels of COMP expression both by the cancer cells and in the stroma was a predictive factor for OS and RFS in patients with intestinal type periampullary adenocarcinoma and colorectal cancer." (PMID 38563861, 2024). "This study aimed to investigate whether this is also the case for colorectal cancer (CRC) and to evaluate the relationship between COMP expression and clinopathological features." (PMID 37207219, 2023). "Moreover, COMP was found for the first time to interact with TAGLN to promote the migration and invasion of colorectal cancer cells." (PMID 32754278, 2020). "Chrysin inhibited COMP, thereby preventing EMT and the malignant progression of colorectal cancer." (PMID 32754278, 2020).